SMIM8 (small integral membrane protein 8)
Synonyms: C6orf162; DKFZP586E1923; dJ102H19.2; C6orf164; dJ102H19.4; LINC01590
Tractability: Antibody: UniProt predicts a signal peptide or a membrane-spanning region. PROTAC: its protein half-life has been measured.
Gene: Protein-coding gene on chromosome 6 (87,322,580 to 87,399,749, forward strand). Ensembl gene ENSG00000111850.
Subcellular location: Membrane
Subcellular location (Human Protein Atlas): Vesicles
Gene Ontology:
Cellular component: mitochondrion; membrane
Genetic constraint (gnomAD): Loss-of-function variants: 8 observed, 8.02 expected, observed/expected ratio (o/e) 1, 90% interval 0.58 to 1.71. That is too few expected variants to judge how well the gene tolerates losing a copy. Missense variants: 126 observed, 122.59 expected, observed/expected ratio (o/e) 1.03, 90% interval 0.89 to 1.19. Synonymous variants: 45 observed, 40.63 expected, observed/expected ratio (o/e) 1.11, 90% interval 0.87 to 1.42.
Homologues: Orthologues: chimpanzee SMIM8 (98% identical), dog SMIM8 (93% identical), pig SMIM8 (92% identical), mouse Smim8 (89% identical), guinea pig SMIM8 (87% identical), rat Smim8 (87% identical), tropical clawed frog smim8 (67% identical), zebrafish smim8 (63% identical), Drosophila melanogaster CG32448 (28% identical).
Diseases named in the same sentence as SMIM8 in open-access papers:
SMIM8 is named in the same sentence as 1 disease in open-access papers, as found by Europe PMC text mining. Sharing a sentence is not in itself a finding about the gene and the disease.
SMIM8 shares sentences with these, for which no sentence is quoted: infection (1 paper).